RIPOR3 (RIPOR family member 3)
Synonyms: C20orf175; C20orf176; FAM65C; dJ530I15.2; dJ530I15.3
Tractability: No criterion of Open Targets' tractability assessment is met for any kind of drug.
Gene: Protein-coding gene on chromosome 20 (50,585,180 to 50,692,021, reverse strand). Ensembl gene ENSG00000042062.
Subcellular location (Human Protein Atlas): Nucleoplasm
Gene Ontology:
Molecular function: protein binding
Genetic constraint (gnomAD): Loss-of-function variants: 92 observed, 107.8 expected, observed/expected ratio (o/e) 0.85, 90% interval 0.72 to 1.01. The upper end of that interval is the gene's LOEUF score, 1.01, which puts it in group 4 of 6, group 1 being the genes least tolerant of losing a copy. Missense variants: 1,230 observed, 1,229.4 expected, observed/expected ratio (o/e) 1, 90% interval 0.95 to 1.05. Synonymous variants: 565 observed, 528.2 expected, observed/expected ratio (o/e) 1.07, 90% interval 1 to 1.15.
Homologues: Orthologues: chimpanzee RIPOR3 (99% identical), macaque RIPOR3 (95% identical), dog RIPOR3 (87% identical), pig RIPOR3 (85% identical), guinea pig RIPOR3 (79% identical), rat Ripor3 (76% identical), mouse Ripor3 (76% identical), rabbit RIPOR3 (73% identical), tropical clawed frog ripor3 (48% identical), zebrafish ripor3 (38% identical), Caenorhabditis elegans Y37A1A.4 (20% identical). Paralogues in human: RIPOR2 (37% identical), RIPOR1 (34% identical).
Diseases named in the same sentence as RIPOR3 in open-access papers:
RIPOR3 is named in the same sentence as 1 disease in open-access papers, as found by Europe PMC text mining. Sharing a sentence is not in itself a finding about the gene and the disease.
RIPOR3 shares sentences with these, for which no sentence is quoted: tumor (1 paper).